PTH (parathyroid hormone)
Diseases named in the same sentence as PTH in open-access papers (continued):
Sharing a sentence is not in itself a finding about the gene and the disease.
relapsing remitting MS (2 papers, 2012 to 2018). "Nevertheless, one of these studies reported lower levels of the bone formation marker osteocalcin, higher bone resorption markers (pyridinoline and deoxypyridinoline), and higher PTH in premenopausal women with relapsing remitting MS compared to controls." (PMID 23029191, 2012). "Parathyroid glands of people with relapsing remitting multiple sclerosis (RRMS) fail to respond to low serum 25-hydroxyvitamin D (25OHD) and low serum calcium, which are stimuli for parathyroid hormone (PTH) secretion." (PMID 30134801, 2018).
renal colic (2 papers, 2018 to 2025). A severe intermittent and spasmodic pain in the lower back radiating to the groin, scrotum, and labia which is most commonly caused by a kidney stone (RENAL CALCULUS) passing through the URETER or by other urinary track blockage. "Here, we report a case of an asymptomatic young woman with previous episodes of renal colic, showing elevated serum PTH levels measured on the DiaSorin LIAISON XL CLIA analyzer despite the other parameters being normal." (PMID 40290309, 2025).
Renal cyst (2 papers, 2019 to 2020). A fluid filled sac in the kidney. "Prevalence of antihypertensive drug users and patients with renal cysts and parathormone (PTH) and alkaline phosphatase levels were higher in patients with GFR of ≥60 than in GFR of <60 mL/min/1.73 m2 (P < 0.05)." (PMID 30761868, 2019).
Respiratory tract infection (2 papers, 2012 to 2022). An infection of the upper or lower respiratory tract. "In addition, normal values of PTH have been reported in the following groups of children with THI: healthy ones, those with acute but mild illness (diarrhoea, respiratory tract infections), and in patients after liver or kidney transplantation." (PMID 22664360, 2012).
rhabdomyolysis (2 papers, 2011 to 2023). Necrosis or disintegration of skeletal muscle often followed by myoglobinuria. "We sought to determine the impact of AKI on FGF-23 and parathyroid hormone (PTH) levels in patients with AKI due to causes other than rhabdomyolysis." (PMID 21906363, 2011).
rheumatic diseases (2 papers, 2022 to 2023). "It is recommended that both vitamin D and PTH be given in rheumatic diseases." (PMID 36815008, 2023).
skin aging (2 papers, 2022 to 2025). The gradual irreversible changes in structure of skin that occur as a result of the passage of time.. "Older adults inherently have reduced vitamin D synthesis capacity due to decreased sun exposure and skin aging, impaired renal 1α-hydroxylase activity, and increased skeletal sensitivity to parathyroid hormone, making them uniquely susceptible to calcium homeostasis disruption caused by phenytoin." (PMID 41158130, 2025).
somatostatinoma (2 papers, 2019). A rare, usually malignant neuroendocrine tumor arizing from delta cells. "Patients diagnosed with somatostatinoma should be screened for other components of MEN-1 by either serum calcium level (parathyroid hormone and ionized calcium level can be added to enhance sensitivity and specificity) or DNA-based genetic testing." (PMID 31210994, 2019). "The other functional PanNET (glucagonoma, VIPoma, somatostatinoma, GRFoma, ACTHoma, PTH-rP secreting tumors or calcitoninoma) are even rarer." (PMID 31593916, 2019).
thymic atrophy (2 papers, 2019 to 2020). "An additional mechanism associated with thymic atrophy caused by PTH is the effect of haematopoietic stem cells." (PMID 30692566, 2019). "Although this is a cross-sectional study, PTH may cause thymus atrophy and contribute to immune abnormality, which may also partially explain the increased mortality due to elevated PTH level." (PMID 30692566, 2019). "In conclusion, we showed that serum PTH concentrations are associated with thymic atrophy." (PMID 30692566, 2019). "Parathyroid hormone (PTH) and fibroblast growth factor 23 (FGF23), which are mineral and bone disorder (MBD)-related factors, affect immune cells and possibly cause thymic atrophy." (PMID 30692566, 2019). "In patients with CKD, serum PTH concentrations were related to thymic atrophy which contributes to immune abnormality." (PMID 30692566, 2019). "A recent study indicated serum PTH concentrations were related to thymus atrophy evaluated by recent thymic emigrants, indicating mineral and bone disorder might be an underling mechanism." (PMID 32660510, 2020). "Further investigation is required to explain the relationship between PTH and thymic atrophy." (PMID 30692566, 2019). "This study showed that thymic atrophy was associated with higher PTH level, but not with FGF23 or ALP level, after adjustment for eGFR, active vitamin D supplementation, and other variables." (PMID 30692566, 2019). "For these reasons, PTH may be involved in the pathogenesis of these complications by inducing immune abnormality through thymic atrophy in addition to regulating bone metabolism." (PMID 30692566, 2019).
thyroid tumor (2 papers, 2022). A benign or malignant neoplasm affecting the thyroid gland. "Second, data regarding preoperative PTH values, parafibromin staining results or Ki67 index values were unavailable for some patients, who were misdiagnosed with thyroid tumors until postoperative histopathological examination or who received the initial surgery at a different hospital in the past." (PMID 36010997, 2022).
vascular dementia (2 papers, 2018 to 2025). A degenerative vascular disorder affecting the brain. "A study from the Uppsala Longitudinal Study of Adult Men (ULSAM) found a significant link between PTH levels and vascular dementia, though the sample size was small." (PMID 41050279, 2025).
Ventricular arrhythmia (2 papers, 2013 to 2014). "In the present study, PTH levels were lower in patientes with ventricular arrhythmias." (PMID 23762460, 2013). "Serum phosphates and iron, PTH level, renal function, hemoglobin and hematocrit, pH, inflammatory markers, proteinuria and microalbuminuria, and osmolarity should be monitored, besides standard 12-lead ECG, in order to prevent ventricular arrhythmia and sudden cardiac death." (PMID 24982887, 2014).
vitamin D metabolism disorders (2 papers, 2022 to 2025). "Nevertheless, assessing 1,25(OH)2D is relevant in diagnosing of vitamin D metabolism disorders, PTH-independent hypercalceamia and hypophosphatemic syndromes." (PMID 40502410, 2025). "The determination of 1,25(OH)2D is clinically relevant in the diagnostics of vitamin D metabolism disorders, PTH-independent hypercalceamia and hypophosphatemic syndromes." (PMID 40502410, 2025).
Vocal cord paralysis (2 papers, 2022 to 2024). A loss of the ability to move the vocal folds. "On the other hand, it also increases the risk of short-term postoperative complications such as vocal cord paralysis and decreased parathyroid hormone (PTH) levels." (PMID 39449000, 2024). "Serum calcium and parathyroid hormone of this case were in the normal ranges, and vocal cord paralysis was not examined by laryngoscopy." (PMID 36213294, 2022).
X-linked hypophosphatemic rickets (2 papers, 2009 to 2021). "Data from tumor-induced osteomalacia (TIO), familial tumoral calcinosis (FTC), and X-linked hypophosphatemic rickets studies have demonstrated the role of FGFR1 and its ligand FGF23 in tightly regulating phosphate balance in conjunction with the parathyroid hormone." (PMID 34199304, 2021).
xerosis (2 papers, 2005 to 2021). "Etiology of uremic pruritus may comprise several factors, including xerosis, peripheral neuropathy, mast cell hyperplasia, increased serum level of histamine, vitamin A, parathyroid hormone (PTH), and certain inflammatory factors, such as interleukin-2 (IL2)." (PMID 34367296, 2021).
Yersinia infection (2 papers, 2022 to 2024). "Based on the KEGG enrichment analysis of key genes, it has been found that several hub signaling pathways, namely, parathyroid hormone synthesis, secretion and action, estrogen signaling, and Yersinia infection, are closely related to pain and may play a significant role in pain management." (PMID 39125922, 2024).
acute bronchiolitis (1 paper, 2024). Acute inflammation of the bronchioles usually caused by the respiratory syncytial virus. "Regarding PTH levels, a statistically significant difference was observed between the control group and the children with acute bronchiolitis, likely due to the high percentage of hypervitaminosis in this group." (PMID 39585042, 2024). "Regarding PTH levels, statistical significance was found between the control group and the acute bronchiolitis group, due to the high percentage of children with hypervitaminosis in this subgroup." (PMID 39585042, 2024).
advanced heart failure (1 paper, 2013). Patients with advanced heart failure have severe limitations, experiences symptoms even while at rest and are mostly bedbound patients. "Advanced heart failure in addition to lung and kidney failure, HTLV-I antibody in serum and increased calcium and parathyroid hormone levels were diagnosed in this patient." (PMID 24470865, 2013).
amenorrhea (1 paper, 2013). The absence of menses in a woman who has achieved reproductive age. "In a stepwise multiple regression, the serum PTH level and amenorrhea at the time of evaluation were the most significant predictors of deoxypyridinoline levels, explaining 36% of its variance." (PMID 23634145, 2013).
aneurysm (1 paper, 2025). Bulging or ballooning in an area of an artery secondary to arterial wall weakening. "Age grouping revealed that Blood parathyroid hormone increased and Blood calcium decreased were mainly in the 45–64 age group and had a stronger signal intensity, while Shunt aneurysm and Shunt infection were relatively weaker." (PMID 40170738, 2025).
ankylosing spondylitis (1 paper, 2021). An autoimmune chronic inflammatory disorder characterized by inflammation in the vertebral joints of the spine and sacroiliac joints. "PTH, which is one of the main determinants of Dkkopf-1, plays a crucial role in bone erosions in RA and a correlation between PTH, Trabecular Bone Score (TBS) and disease activity has been found in ankylosing spondylitis (AS)." (PMID 34093428, 2021).
anxiety disorder (1 paper, 2024). A category of psychiatric disorders which are characterized by anxious feelings or fear often accompanied by physical symptoms associated with anxiety. "Thus, women can be said to be more prone to anxiety disorders compared with men, particularly in the group with PTH >400 pg/ml." (PMID 38681457, 2024).
Aortic dissection (1 paper, 2025). Aortic dissection refers to a tear in the intimal layer of the aorta causing a separation between the intima and the medial layers of the aorta. "Among the other SOCs, the occurrence of pathological fracture, aortic dissection, increased parathyroid hormone in the blood, and marasmus after romosozumab treatment were noteworthy, as they occurred quite frequently and with high signal strength." (PMID 39808360, 2025).
aortic valve disease (1 paper, 2025). "Despite the extensive research on the role of key determinants of calcium metabolism in the pathophysiology of AoS, no studies to date have directly examined the relationship between PTH and frailty in older adults with aortic valve disease." (PMID 39860340, 2025).
arrhythmogenic right ventricular cardiomyopathy (1 paper, 2022). "The glycosaminoglycan degradation, arrhythmogenic right ventricular cardiomyopathy, axon guidance, autophagy–yeast, cAMP signaling pathway, parathyroid hormone synthesis, secretion and action, and pathways in cancer were among the enriched KEGG pathways." (PMID 35528543, 2022).
autoimmune encephalitis (1 paper, 2020). Inflammation of the brain secondary to an immune response triggered by the body itself. "The blood count, morphology of erythrocyte, blood biochemistry, ceruloplasmin, thyroid function, parathyroid hormone, metal toxin analysis, ganglioside antibody spectrum, paraneoplastic antibody spectrum, and antibodies of autoimmune encephalitis were normal." (PMID 32307925, 2020). "The blood count, blood biochemistry, thyroid function, parathyroid hormone, metal toxin analysis, blood acylcarnitines and urine organic acid profiles, ganglioside antibody spectrum, paraneoplastic antibody spectrum, and antibodies of autoimmune encephalitis were all negative to abnormalities." (PMID 32307925, 2020).
bacteremia (1 paper, 2020). "Two subjects experienced SAEs, one administered TransCon PTH 12 μg PTH(1‐34) developed catheter‐site phlebitis leading to hospitalization and one administered placebo developed bacteremia; neither SAE was assessed to be related to study drug and both resolved without sequelae." (PMID 32212275, 2020).
beta-thalassemia major (1 paper, 2023). Beta-thalassemia (BT) major is a severe early-onset form of BT characterized by severe anemia requiring regular red blood cell transfusions. "We evaluated the association of vitamin D and parathormone (PTH) levels with cardiac iron and function in beta-thalassemia major (β-TM) patients." (PMID 38132240, 2023).
bipolar I disorder (1 paper, 2020). A bipolar disorder that is characterized by at least one manic or mixed episode. "According to the univariate analyses, several severity and outcome indexes, including the diagnosis of bipolar I disorder, the presence of psychotic characteristics in acute phases, seasonality and history of suicide attempts, are associated with increased levels of PTH." (PMID 32630307, 2020).
brain inflammation (1 paper, 2023). "To understand how PTH1-34 treatments affect brain inflammation in 5XFAD mice, we investigated PTH1-34’s effect on systemic inflammation, since PTH is a hormone with systemic effects, particularly in bone cells." (PMID 36918976, 2023).
brain injury (1 paper, 2018). Acute and chronic (see also brain INJURIES, CHRONIC) injuries to the brain, including the cerebral hemispheres, CEREBELLUM, and brain STEM. "Traumatic brain injury-induced skeletal changes seems to be dependent in part on the variations in parathyroid hormone (PTH) and vitamin D axis." (PMID 29556212, 2018).
brain tumors (1 paper, 2024). "The findings suggest that higher PTH levels are associated with inferior EFS in certain cancer subtypes, including malignant primary brain tumors, embryonal, and lymphatic malignancies." (PMID 39141058, 2024). "In the group of malignant primary brain tumors (N = 258) the mean 5-year EFS was 46.9% (37.3%–60.0%) in PTH+ compared to the PTH− group (64.3%; 55.4.–74.5%)." (PMID 39141058, 2024).
central precocious puberty (1 paper, 2022). "A cross-sectional clinical and blood testing study (calcium, phosphorus, 25(OH)D and PTH) was carried out in 78 girls with central precocious puberty (CPP group), aged 6.1–7.9 years." (PMID 35750999, 2022).
Cerebral ischemia (1 paper, 2014). Restriction of arterial blood supply to the brain associated with insufficient oxygenation to support the metabolic requirements of the tissue. "Since cerebral ischemia may damage the BBB and increase its permeability, PTH circulating in the blood may leak into the brain tissue." (PMID 24503654, 2014). "At present, there is no report on whether PTH-mobilized bone marrow cells may have beneficial effects after cerebral ischemia." (PMID 24503654, 2014).
cervical (1 paper, 2012). "In-hospital death: in patients with cervical HF PTH (OR = 1.40; 95% CI 1.04-1.88; p = 0.027) and leptin (OR = 0.81; 95% CI 0.66-0.99; p = 0.040) and PTH (OR = 1.34; 95% CI 1.03-1.73; p = 0.027) in patients with trochanteric HF." (PMID 22333003, 2012).
cervical dysplasia (1 paper, 2025). "The final model, adjusted for the modifying effect of PTH, showed that the interaction between cervical dysplasia and HIV status was significant (p = 0.005)." (PMID 40507578, 2025).
cervical tumors (1 paper, 2014). "If not contraindicated, PTH–FNA could be helpful in the differential diagnosis of equivocal cervical tumors." (PMID 25379182, 2014).
Cholecystitis (1 paper, 2026). The presence of inflammatory changes in the gallbladder. "Decreased cortical thickness and surface area of the paracentral lobule were nominally associated with genetically predicted cholecystitis (PTH = .024; PSA = .042)." (PMID 41686633, 2026).
chondrodysplasia (1 paper, 2012). "We decided to analyze the PTHR1 gene encoding PTH/PTHrP receptor for parathyroid hormone related peptide (PTHrP) and parathyroid hormone (PTH), since mutations in this gene are a known cause of Jansen metaphyseal chondrodysplasia." (PMID 22528043, 2012).
chronic autoimmune hepatitis (1 paper, 2025). "Two other case reports published between 2023 and 2024 showed falsely elevated PTH levels due to immunoassay interference in two patients affected by psoriatic arthritis and chronic autoimmune hepatitis, respectively." (PMID 40290309, 2025).
chronic gastritis (1 paper, 2023). Inflammation of the stomach that is chronic in nature. "The correlation between osteoporosis and chronic gastritis may be due to the ability of parathyroid hormone to stimulate gastrin secretion, as well as an increased pro-inflammatory profile in patients with chronic gastritis, which stimulates bone resorption." (PMID 37958752, 2023).
cystinosis (1 paper, 2024). Cystinosis is a metabolic disease characterized by an accumulation of cystine inside the lysosomes, causing damage in different organs and tissues, particularly in the kidneys and eyes. "As expected, patients with cystinosis had significant growth retardation and decreased renal function (however, with rather preserved renal function for this disease) as compared to controls, but age was not different, as well as ALP, PTH, and 25 OH vitamin D levels." (PMID 39540998, 2024).
cystinuria (1 paper, 2017). Cystinuria is a renal tubular amino acid transport disorder characterized by recurrent formation of kidneys cystine stones. "The laboratory investigation consisted of at least two samples of blood and 24-hour urine to assess calcium, uric acid, citrate and creatinine levels, qualitative cystinuria, urinary pH following fasting and 12-hour water restriction, urine culture, serum creatinine and parathyroid hormone." (PMID 29267427, 2017).
cytomegalovirus infection (1 paper, 2024). A herpesvirus infection caused by Cytomegalovirus. "The KEGG analysis revealed that the DEGs were enriched for a number of pathways, including the cAMP signaling system, the synthesis, secretion, and action of parathyroid hormone, glioma, human T-cell leukemia virus 1, and human cytomegalovirus infection." (PMID 37165489, 2024).
duodenal tumors (1 paper, 2017). "The patient in this case was first suspected of having MEN1 based on the clinical findings of multiple peptic lesions accompanied by high levels of serum gastrin, calcium, and intact PTH, pancreatic and duodenal tumors suspected for NETs, and a urinary tract stone." (PMID 28270118, 2017).
enterocolitis (1 paper, 2022). An inflammatory process affecting the small intestine and colon. "Increased plasma endotoxin concentrations in horses with enterocolitis and increased pro-inflammatory mediators may indirectly and variably suppress PTH secretion in horses." (PMID 35739816, 2022).
familial hypoparathyroidism (1 paper, 2024). A rare heterogeneous group of metabolic disorders characterized by abnormal calcium metabolism due to deficient secretion of parathormone (PTH), without other endocrine disorders or developmental defects. "Testing for mutations in genes associated with familial hypoparathyroidism, such as CaSR, GCM2, or PTH, should be considered to rule out an inherited etiology." (PMID 39416579, 2024).